CNGA1 (cyclic nucleotide gated channel subunit alpha 1)
Description:
Pore-forming subunit of the rod cyclic nucleotide-gated channel. Mediates rod photoresponses at dim light converting transient changes in intracellular cGMP levels into electrical signals. In the dark, cGMP levels are high and keep the channel open enabling a steady inward current carried by Na(+) and Ca(2+) ions that leads to membrane depolarization and neurotransmitter release from synaptic terminals. Upon photon absorption cGMP levels decline leading to channel closure and membrane hyperpolarization that ultimately slows neurotransmitter release and signals the presence of light, the end point of the phototransduction cascade. Conducts cGMP- and cAMP-gated ion currents, with permeability for monovalent and divalent cations. The selectivity for Ca(2+) over Na(+) increases with cGMP concentrations, whereas the selectivity among monovalent ions is independent of the cGMP levels.
Synonyms: CNG-1; CNG1; CNCG; CNCG1; RCNC1; RCNCa; RP49; RCNCalpha
Tractability: Small molecule: a structure with a bound ligand is known; it belongs to a druggable protein family. Antibody: UniProt places it where antibodies can reach, with high confidence; its Gene Ontology location is reachable by antibodies, with high confidence; UniProt predicts a signal peptide or a membrane-spanning region.
Gene: Protein-coding gene on chromosome 4 (47,935,128 to 48,017,301, reverse strand). Ensembl gene ENSG00000198515.
Subcellular location: Cell membrane
Subcellular location (Human Protein Atlas): Mid piece; Nucleoplasm; Principal piece; Vesicles; Mitotic spindle; Plasma membrane; Primary cilium; Primary cilium tip
Pathways (Reactome):
Sensory Perception: Activation of the phototransduction cascade; Inactivation, recovery and regulation of the phototransduction cascade
Gene Ontology:
Molecular function: cAMP binding; cGMP binding; intracellularly cAMP-activated cation channel activity; intracellularly cGMP-activated cation channel activity; protein binding; intracellularly cyclic nucleotide-activated monoatomic cation channel activity; monoatomic ion channel activity
Biological process: visual perception; calcium ion transport; monoatomic cation transmembrane transport; sensory perception of chemical stimulus; sodium ion transport; monoatomic ion transport; transmembrane transport
Cellular component: plasma membrane; intracellular cyclic nucleotide activated cation channel complex; photoreceptor outer segment membrane; rod photoreceptor outer segment; membrane; photoreceptor outer segment
Genetic constraint (gnomAD): Loss-of-function variants: 27 observed, 47.78 expected, observed/expected ratio (o/e) 0.57, 90% interval 0.41 to 0.78. The upper end of that interval is the gene's LOEUF score, 0.78, which puts it in group 3 of 6, group 1 being the genes least tolerant of losing a copy. Missense variants: 649 observed, 722.89 expected, observed/expected ratio (o/e) 0.9, 90% interval 0.84 to 0.96. Synonymous variants: 212 observed, 260.11 expected, observed/expected ratio (o/e) 0.82, 90% interval 0.73 to 0.91.
Gene-disease validity (ClinGen):
ClinGen rates the evidence that CNGA1 causes each of these diseases.
CNGA1-related retinopathy (autosomal recessive): Definitive. An inherited retinopathy caused by bi-allelic variants in the CNGA1 gene.
Homologues: Orthologues: chimpanzee CNGA1 (99% identical), macaque CNGA1 (98% identical), chimpanzee CNGA1 (98% identical), dog CNGA1 (92% identical), pig CNGA1 (92% identical), rabbit CNGA1 (91% identical), mouse Cnga1 (90% identical), rat Cnga1 (90% identical), tropical clawed frog cnga1 (74% identical), zebrafish cnga1b (64% identical), guinea pig CNGA1 (60% identical), zebrafish cnga1a (60% identical), and 11 more. Paralogues in human: CNGA3 (61% identical), CNGA2 (56% identical), CNGA4 (42% identical), CNGB1 (26% identical), CNGB3 (26% identical), HCN1 (22% identical), KCNH7 (21% identical), HCN4 (21% identical), HCN2 (21% identical), KCNH2 (19% identical), KCNH3 (19% identical), HCN3 (19% identical), and 5 more.
Diseases named in the same sentence as CNGA1 in open-access papers:
CNGA1 is named in the same sentence as 17 diseases in open-access papers, as found by Europe PMC text mining. Sharing a sentence is not in itself a finding about the gene and the disease. The quoted sentences say what the papers report.
retinitis pigmentosa (8 papers, 2014 to 2026). Retinitis pigmentosa (RP) is an inherited retinal dystrophy leading to progressive loss of the photoreceptors and retinal pigment epithelium and resulting in blindness usually after several decades. "Ophthalmic findings in five patients with retinitis pigmentosa with compound heterozygous or homozygous CNGA1 mutations." (PMID 25268133, 2014). "The co-occurrence of PD with retinitis pigmentosa may be related to mutations in cyclic nucleotide gated channel subunit alpha 1 (CNGA1) and SNCAIP genes." (PMID 40243562, 2025). "A novel compound mutation in CNGA1 gene, coding for the cGMP-gated ion channel protein, results in a protein product that is not targeted to the plasma membrane, which would be deleterious to rod photoreceptors leading to retinitis pigmentosa (RP)." (PMID 26802146, 2016). "In an Indian family suffering from retinitis pigmentosa, we identified a missense variation in CNGA1 affecting the cyclic nucleotide binding domain (CNBD) and characterized a mouse model developed with mutated CNBD." (PMID 36115851, 2022). "Interestingly, RGR, CNGA1, and RLBP1 play an important role in retinitis pigmentosa." (PMID 37179305, 2023).
autosomal recessive retinitis pigmentosa (5 papers, 2014 to 2026). Autosomal recessive retinitis pigmentosa (RP) is an autosomally recessive inherited retinal dystrophy leading to progressive loss of the photoreceptors and retinal pigment epithelium and resulting in blindness usually after several decades. "In the present study, we have identified a family (DKRRP2) with autosomal recessive retinitis pigmentosa suffering from a homozygous c.1525 G > A (NM_001379270.1) missense mutation in CNGA1 leading to substitution of a Gly at position 509 by an Arg." (PMID 36115851, 2022). "Mutations in the remaining four genes, namely, SLCO1B1, CNGA1, PRSS12, and PEX1, have associations with autosomal diseases, such as autosomal recessive retinitis pigmentosa and non-syndromic intellectual disability." (PMID 35912179, 2022). "A gene panel analysis comprising 105 known RP genes was used to analyze a family with autosomal-recessive retinitis pigmentosa (arRP) and revealed that CNGA1 was affected." (PMID 36115851, 2022).
retinal degeneration (5 papers, 2014 to 2023). Degeneration of the retina. "Knockout mutation of Nrl leads to the loss of rod cells while mutations in Gnb3, Cnga1, and Cngb1 have been shown to lead to night blindness in humans and retinal degeneration in chickens." (PMID 36576130, 2022). "Considering the phenotypes related to CNGA1 mutations, retina degeneration in the macular region differed from previous reports." (PMID 26802146, 2016). "Mutations within the CNGA1 gene cause the RP49 form that presents with an early onset and severe retinal degeneration." (PMID 26802146, 2016). "Retinal degeneration in the macular region and severely decreased BCVA occurred in 3/5 patients suggesting that the advanced stage of CNGA1 mutations included degeneration of the entire retina with both rod and cone photoreceptors." (PMID 25268133, 2014).
retinal diseases (4 papers, 2007 to 2026). "Additionally, a study exploring the genetic landscape of retinal diseases in northwestern Pakistan identified prevalent mutations in genes such as ABCA4, BBS2 and CNGA1 as the most frequently associated IRD genes." (PMID 40141357, 2025).
hereditary retinal dystrophy (2 papers, 2014 to 2022). "The prevalence of CNGA1 mutations in a Spanish arRP population was 2.1% (1 of 46 patients), whereas that in a Chinese population with hereditary retinal dystrophy was 4.0% (1 of 25 patients)." (PMID 25268133, 2014).
achromatopsia (1 paper, 2023). Achromatopsia (ACHM) is a rare autosomal recessive retinal disorder characterized by color blindness, nystagmus, photophobia, and severely reduced visual acuity due to the absence or impairment of cone function. "Four of the CNG channel genes are linked to inherited retinal disorders (IRD): mutations in CNGA1 and CNGB1 are known to cause retinitis pigmentosa (RP) and mutations in CNGA3 and CNGB3 cause achromatopsia (ACHM)." (PMID 36830806, 2023).
Blindness (1 paper, 2022). Blindness is the condition of lacking visual perception defined as a profound reduction in visual perception. "In summary, ERG analysis indicates a lack of rod photoreceptor-driven responses in Cnga1 mutant mice as early as PW3 and reveals a secondary, slowly progressive loss of cone-mediated light responses, leading to complete blindness after PM9." (PMID 36115851, 2022).
COVID-19 (1 paper, 2025). A disease caused by infection with severe acute respiratory syndrome coronavirus 2. "FXR/RXR, DPP4, JAK2, and ACE are associated with COVID-19, while CNGA1, BLT1, COX2, and 5-LOX are linked to pharyngitis." (PMID 40076279, 2025). "The results demonstrated that high doses of isochlorogenic acid C inhibited FXR/RXR, DPP4, JAK2, ACE, CNGA1, BLT1, COX-2, and 5-LOX, suggesting its potential to modulate COVID-19-related inflammatory pathways." (PMID 40076279, 2025).
viral infection (1 paper, 2013). "Using a sorting approach independent from genetically encoded fluorochromes with Cacna2d4 or Cnga1, for example, to enrich in vitro generated photoreceptors would avoid the need for viral infection and genetic manipulation of donor cells, and lead to easier clinical application." (PMID 24146539, 2013).
tumor (1 paper, 2018). "In addition, the expression levels of rod-enriched genes, including NRL, NR2E3, CNGA1, and PDE6G, were depleted in organoids, consistent with tumor, but high in normal retina, where rods outnumber cones." (PMID 30353124, 2018).
CNGA1 also shares sentences with these, for which no sentence is quoted: night blindness (3 papers); infection (2); Bardet-Biedl syndrome (1); Chorioretinal atrophy (1); Intellectual disability (1); pharyngitis (1); retinal dystrophy (1).